APOE (apolipoprotein E)
Diseases named in the same sentence as APOE in open-access papers (continued):
Sharing a sentence is not in itself a finding about the gene and the disease.
cognitive decline (continued). "While one study reported a protective effect of APOE ε2 among women in predicting performance on a delayed recall task, another observed a protective effect of APOE ε2 against cognitive decline in men." (PMID 41226628, 2025). "The most studied genetic factor is Apolipoprotein E (APOE) allele epsilon ε4 (APOE4), which is known to increase the risk of CVD and cognitive decline." (PMID 40085364, 2025). "Patients involved in immunovascular signaling (MMP8), synaptic vesicle fusion (SNAP23) and lipid trafficking (APOB) pathways relevant to APOE biology and cognitive decline." (PMID 40665048, 2025). "Insight into APOE-related pathways is important to unravel pathophysiology and identify therapeutic targets against late-life cognitive decline." (PMID 40344552, 2025). "An AD PRS has been found to be related to longitudinal cognitive decline (global or domain-specific), independently of the APOE genotype, in six studies." (PMID 39940679, 2025). "Mediation analysis further suggests that the interaction between sleep duration and APOE genotype influences LC-FC connectivity, mediating the relationship between age and cognitive decline." (PMID 40994826, 2025). "Impaired ABCA1 function (due to polymorphisms or downregulation in disease states) leads to reduced ApoE lipidation, diminished Aβ clearance, and increased Aβ and tau pathology, and accelerates cognitive decline." (PMID 41226793, 2025). "In apolipoprotein E ε4 (APOE-ε4) carriers with subjective cognitive decline, in older adults showed that adding EGCG to a 12-mo lifestyle program led to preliminary cognitive stabilization, though full data are pending." (PMID 41106481, 2025). "Limbic tracts (eg, cingulum, fornix) were most strongly associated across domains, and abnormal AD endophenotypes (eg, SPARE-AD index, APOE ε4 status, amyloid positivity) exacerbated cognitive decline." (PMID 40513084, 2025). "The faster p‐tau217 increase in APOE ɛ4 carriers is in accordance with the accelerated cognitive decline of APOE ɛ4 carriers, supporting the notion that p‐tau217 is superior to the other p‐tau analytes to measure disease progression." (PMID 41451854, 2025). "The homozygous case, ATX-05, with 27/27 CAG repeats in the ATXN2, consisted of patients that were 67 years old on average and presented with significant cognitive decline, reflected by a MoCA score of 8.5, and was also homozygous E3/E3 for APOE." (PMID 41009775, 2025). "This suggests that even among NHW individuals with lower cognitive ability, the broader trend of cognitive decline related to European ancestry around APOE ε4 persists." (PMID 40697576, 2025). "Specifically, Haller, Montandon suggested that APOE genotype was solely related to posterior cingulate cortex GM atrophy in healthy individuals who exhibited cognitive decline." (PMID 40167963, 2025). "Free-water imaging of the NBM emerges as a sensitive, non-invasive biomarker capable of detecting these APOE-modulated microstructural changes before overt atrophy or cognitive decline." (PMID 41035826, 2025). "Regarding biomarker progression, a recent study in the Colombian kindred found that APOE4 accelerates age-related plasma NfL increases and APOE ε2 attenuates the relationship between higher plasma NfL levels and cognitive decline in ADAD." (PMID 40103931, 2025). "White matter FW measures interacted with baseline diagnosis, gray matter atrophy, APOE ε4 status, and amyloid positivity to predict poorer cognitive performance and accelerated cognitive decline." (PMID 40513084, 2025). "Chemotherapy-induced damage interacts with pre-existing vulnerabilities, such as APOE ε4 or aging, to exacerbate cognitive decline." (PMID 41333365, 2025). "Multiple studies have confirmed that APOC1 is involved in amyloid-β (Aβ) accumulation and contributes to cognitive decline and memory impairment, similar to the effects observed with APOE ε4." (PMID 40369256, 2025).
cognitive decline (continued). "Longitudinally, APOE E4 predicted cognitive decline (p = 0.015), and TOMM40 haplotypes correlated with motor deficits." (PMID 41009775, 2025). "That is, male ε2 carriers experienced more cognitive decline than non-ε2 carriers, finding evidence of an adverse effect of APOE ε2 on cognition in males." (PMID 41226628, 2025). "This differential impact is discussed as a preclinical indicator of cognitive decline in female APOE ε4 carriers." (PMID 41226628, 2025). "In recent years, studies using extensive neuropsychological tests have shown faster cognitive decline with APOE e4 carriers in patients with PD." (PMID 40722695, 2025). "In the present study, we controlled for educational attainment to isolate the effects of APOE and Klotho genotype and its interaction with sex and age on cognitive decline." (PMID 39903109, 2025). "Two other studies attempted to investigate the inter-relations of Aβ levels, structural changes, the APOE genotype, and cognitive decline." (PMID 40167963, 2025). "SHAP analysis identified clinically relevant features, such as RAVLT scores and APOE ε4 status, that are well-documented predictors of cognitive decline." (PMID 40228177, 2025). "While some of these factors are genetically determined [e.g., apolipoprotein E (APOE)], others, such as physical activity, nutrition, or intellectual engagement, can be modified to promote brain health and mitigate cognitive decline across the lifespan." (PMID 40874237, 2025). "In the current study, we investigated the relationship between APOE ε4 genotype, lifestyle and cognitive decline." (PMID 39639910, 2024). "We also found that elevated CSF ferritin predicted accelerated cognitive decline over 7 years in pre-symptomatic APOE ε4 carriers and was able to discriminate stable from cognitively declining subjects." (PMID 35484240, 2024). "The research indicates that possessing APOE ε4 alters the impact of everyday life factors on cognitive decline." (PMID 39639910, 2024). "Cognitive decline is common in Parkinson’s disease (PD) and its genetic risk factors are not well known to date, besides variants in the GBA and APOE genes." (PMID 38177146, 2024). "Stronger predictive value of Aβ pathology (A+ alone) than tau accumulation (T+ alone) for longitudinal cognitive decline in APOE ε4 carriers." (PMID 39014268, 2024). "This might be explained by the fact that APOE ɛ4 positivity is a great risk factor for hippocampal atrophy regardless of cognitive disease stage and therefore, in APOE ɛ4 negative patients, atrophy will to a higher degree be associated with progression of cognitive decline." (PMID 39011362, 2024). "One study found brain APOE mRNA increases during the mild cognitive impairment (MCI) syndrome that represents the first objectively detectable stage of AD cognitive decline, while another reported increased APOE mRNA in demented AD patient brains." (PMID 39441557, 2024). "First, the APOE ε4 genetic factor contributes to the abnormal accumulation of pathological markers like tau, thereby triggering cognitive decline." (PMID 38894849, 2024). "The age at onset of AD and neuropathologic progression and the rate of cognitive decline were predicted by the ApoE genotype." (PMID 38376028, 2024). "The progressive cognitive decline of PD is likely due to multiple molecular processes, among which apolipoprotein E (ApoE) has been shown as a vital gene for cognitive performance in PD." (PMID 38988604, 2024). "Our results suggest a contributing role of low testosterone levels in cognitive decline in female APOE-ε4 carriers and, thus, stress the importance of considering APOE-ε4 status when examining the role of testosterone in brain health, particularly in women." (PMID 38835072, 2024). "Asymptomatic carriers of AD genetic risk factors, such as the apolipoprotein E ε4 allele (APOE4) or a parental family history of AD, tend to show neural changes and cognitive decline in executive function over time." (PMID 39458427, 2024).
cognitive decline (continued). "Together with findings in AD cases, we can help predict future cognitive decline and neurodegeneration due to distinct epigenetic profiles in different APOE genotype subgroups." (PMID 38424036, 2024). "One study reported NRP1 to interact with APOE-e4 in cognition as higher levels of NRP1 correlated to cognitive decline in patients with the APOE-e4 gene." (PMID 37280551, 2023). "The cognitive trajectories of APOE e2+ and e2− PSEN1 E280A mutation carriers diverged at 41.1 years, such that APOE e2+ PSEN1 carriers had delayed age-related global cognitive decline." (PMID 37612284, 2023). "Our findings suggest that within PSEN1 E280A carriers, age-related cognitive decline begins earlier in those who are APOE e4+ than for those with other APOE genotypes, including those who are homozygous e3 and e2+." (PMID 37612284, 2023). "Given the lower allele frequency and smaller effect size of ε2, few studies have explored sex- and race-specific APOE ε2 effects on cognitive decline." (PMID 37459083, 2023). "In our analysis of accelerated cognitive decline GWAS, we identified two genome-wide significant loci: APOE locus (chromosome 19 p13.32) and rs144614292 (chromosome 11 p15.1)." (PMID 37720047, 2023). "The data suggested that diet control and/or swimming exercise significantly alleviated cognitive decline in ApoE-/- mice by maintaining the structural integrity of white matter in the hippocampus." (PMID 36999158, 2023). "Carriers of APOE ε4 and GBA mutations had faster cognitive decline and were at higher risk of progression to dementia, whereas no significant gene-related effects were observed for MAPT and SNCA rs356219." (PMID 38203667, 2023). "Another study has found that among HIV-positive patients who are ApoE*ε4 carriers, there is an elevation of TC, LDL-C, and TG which is associated with faster rates of cognitive decline." (PMID 37134097, 2023). "Increased physical activity has been shown to attenuate APOE ε4-related vulnerability to early cognitive decline in patients with PD." (PMID 38203667, 2023). "Only three prior studies have examined interactions between CR proxy measures and APOE-ε4 genotype in relationship to longitudinal cognitive decline among individuals with normal cognition at baseline." (PMID 36978190, 2023). "Our key finding is that APOE e4 status was the single most important factor determining longitudinal cognitive decline when all of the predictors were modelled simultaneously." (PMID 36481934, 2023). "Finally, APOE-ε4 carriers may have higher levels of underlying tau pathology and cerebrovascular disease that could be hypothesized as possible mechanisms underlying cognitive decline in those individuals." (PMID 36856866, 2023). "We found evidence of effect modification by APOE status; a significantly greater HR for incident cognitive decline in the MBI‐psychosis group was present only in individuals who carry at least one ε4 allele." (PMID 37139261, 2023). "This suggests that the direct effects of APOE-ε2 genotype on cognitive trajectories are more evident in older populations, among whom cognitive decline is more prevalent." (PMID 36978190, 2023). "In this line, in humans, CSF markers of BBB pericyte injury predict future cognitive decline only in APOE ε4 carriers." (PMID 36707869, 2023). "In line with this, we found a significant interaction between APOE-ε4 and VR Aβ accumulation in the striatum with regard to cognitive decline." (PMID 36856866, 2023). "The IRAP study longitudinal component is ongoing and examination of the inter-relationship of SCD with APOE ε4 on objectively measured cognitive decline is warranted." (PMID 36819726, 2023). "The results demonstrated that consumption of a HFD for a long time leads to memory and learning performance loss, and diet control and/or swimming exercise significantly alleviated cognitive decline in ApoE-/- mice." (PMID 36999158, 2023).
cognitive decline (continued). "In conclusion, our findings provide evidence for the role of both GBA and APOE in the rate of cognitive decline in the general PD population." (PMID 35106798, 2022). "Altogether, our results highlight that the regulation of fatty acids and related metabolic pathways during ageing and cognitive decline depends on complex inter-relationships between the ApoE-ε4 genotype and sex." (PMID 34980257, 2022). "A recent study utilizing data from PPMI demonstrated that increased physical activity attenuated APOE E4-related vulnerability to cognitive decline in individuals with PD." (PMID 36203214, 2022). "For example, it has been shown that apolipoprotein E (APOE) ε4 carriers have accelerated cognitive decline, while APOE ε2 carriers have decelerated cognitive decline compared to ε3 carriers in middle aged and older adults." (PMID 36446774, 2022). "A better understanding of the ApoE-ɛ4 and sex dependent modulation of metabolism is essential to elucidate the individual variability in the onset of cognitive decline, which would help develop personalized therapeutic approaches." (PMID 34980257, 2022). "One such study found that a combination of ApoE genotype and functional MRI (fMRI) was the most effective predictor for future cognitive decline." (PMID 36376083, 2022). "A recent re-analysis of patient-level data from multiple AD clinical trials found that long-term use of various statins resulted in lower rates of cognitive decline, with potentially greater therapeutic efficacy in APOE ε4/ε4 carriers." (PMID 35404972, 2022). "The AD-RAI was significantly correlated with cognition, and had a synergistic effect with APOE-ε4 to predict the rate of cognitive decline." (PMID 35572149, 2022). "A previous study has proved that the apolipoprotein E (APOE) ε4 allele is a genetic risk factor for AD, whereas educational attainments have protective effects against cognitive decline in aging and patients with AD." (PMID 35586480, 2022). "It is also supported by another study, in which a combination of ApoE genotype and task-based fMRI was identified as the best predictor of cognitive decline in healthy older adults." (PMID 36376083, 2022). "For example, the Catechol-O-methyltransferase genotype was found to be related to executive-attention function, and the apolipoprotein E genotype is related to cognitive decline, especially the posterior cortical dysfunction, in the PD population." (PMID 36147702, 2022). "Common genetic variance in apolipoprotein E (APOE), β-glucocerebrosidase (GBA), microtubule-associated protein tau (MAPT), and α-synuclein (SNCA) has been linked to cognitive decline in Parkinson’s disease (PD), although studies have yielded mixed esults." (PMID 35106798, 2022). "C1q-apoE complexes formation correlates with cognitive decline and suppression of complement protein C5 ameliorated inflammation." (PMID 36153580, 2022). "Although carriership of the APOE-ɛ4 allele is the largest genetic risk factor of AD, PRS of AD has been also associated with cognitive decline, hippocampal function, and core AD CSF biomarkers." (PMID 36345036, 2022). "Since there were differences in AD biomarker trajectories depending on sex and APOE genotype, our findings will help to design individualized therapeutic and preventive strategies to ameliorate AD biomarkers, resulting in cognitive decline." (PMID 35197846, 2022). "Specifically, we predicted that APOE ε4 carriers would show cognitive decline over the course of the study and that this decline would be less in those receiving active treatment with evolocumab." (PMID 35404972, 2022). "The importance of these interventions in ApoE ε4 individuals with early Alzheimer’s or cognitive decline has been discussed and published previously by Dr. Dale Bredesen." (PMID 35517054, 2022).
cognitive decline (continued). "As expected, a significantly increased prevalence of patients with cognitive decline (P < 0.05), APOE-ε4 carriage status (P < 0.01), and poorer MMSE (P < 0.0001) was observed in the Aβ-positive group." (PMID 35130933, 2022). "BBB breakdown contributes to cognitive decline in apolipoprotein E (APOE)-4 carriers by Aβ-independent pathology." (PMID 35269541, 2022). "APOE ε4 carriers also presented with significantly greater rates of cognitive decline in MAP, CHAP-White and CHAP-Black (all p < 0.0001)." (PMID 35807939, 2022). "The reason for sex differences in observed relations between ApoE ε4 is not known, but an interaction effect between sex hormone oestrogen and APOE‐ε4 on cognitive decline has been reported." (PMID 36045102, 2022). "In this context, LRP8 KO/ApoE KO mice have shown cognitive decline greater than that observed in ApoE single-KO mice as indicated by behavioral tests." (PMID 36012187, 2022). "For example, the E4 variant of apolipoprotein E (APOE), the main susceptibility gene for AD, leads to accelerated BBBD and cognitive decline in humans and animals." (PMID 35682895, 2022). "The aim of our study was to explore the dynamic functional alterations in the brain in patients with subjective cognitive decline (SCD) and their relationship to apolipoprotein E (APOE) €4 alleles." (PMID 35356298, 2022). "Recent evidence has also shown that having a positive outlook on aging, such as a sense of purpose, amplified the protective effect of APOE ɛ2 against cognitive decline." (PMID 36512526, 2022). "It is generally believed that high-fat diets promote obesity and neuroinflammation and induce a cognitive decline in ApoE–/– mice." (PMID 35252286, 2022). "A pattern of more cognitive decline, mimicking the process of AD, has been found in clinically normal APOE ε4 carriers." (PMID 35149974, 2022). "The three case studies above, all purposely from individuals with ApoE ε4, illustrate that it is possible to improve indices of cognitive decline and improve patient well-being and function." (PMID 35517054, 2022). "There were differences in the predictive effects of NfL baseline levels/change rate on cognitive decline in PD through subgroup analyses that considered age, gender, educated years, and APOE ε4 carrier status, respectively." (PMID 36589544, 2022). "Future research should focus on populations with increased risk of cognitive decline (e.g., people with MCI or ApoE ε4 genotype) and modifiable risk factors, such as their dietary habits." (PMID 35057514, 2022). "Using the largest pooled study of population-based cohorts to date, we have provided data on the impact of genetic variants in APOE, GBA, MAPT and SNCA on cognitive decline over the first 10 years of PD." (PMID 35106798, 2022). "An interaction effect between estrogen and APOE-ε4 has been reported for cognitive decline and carotid atherosclerosis in older women." (PMID 35276898, 2022). "We used ordinal logistic regression models to estimate the effects of leisure activities, APOE ε4, and their interaction on cognitive decline, statistically adjusted for a range of potential confounders." (PMID 34616288, 2021). "During patient selection for this proteomic analysis, we payed special attention to ApoE genetype, olfactory function, and rGSK‐3β(T/S9), because changes of these factors are correlated to the cognitive decline in T2DM patients." (PMID 34528736, 2021). "APOE-ε4 carriers show cognitive decline across several cognitive tests, for example, taking longer to complete the Trail Marking Test and making fewer correct matches in the Digit symbol substitution test." (PMID 34301914, 2021). "According to previous studies, there is controversy about the effect of APOE ε4 on rate of cognitive decline in AD." (PMID 34127075, 2021).